DSP (desmoplakin)
Diseases named in the same sentence as DSP in open-access papers (continued):
Sharing a sentence is not in itself a finding about the gene and the disease.
cardiomyopathy (continued). "Two probands had a diagnosis of cardiomyopathy, with woolly hair and keratoderma (OMIM 605676) and were compound heterozygous, each carrying a DSPtv (p.Arg2229Serfs*32 or p.Tyr28Alafs*66) and a DSP splice site variant (the same c.273+5G>A in both)." (PMID 36580316, 2023). "ACM caused by mutations in the DSP gene encoding desmoplakin (DSP) is characterized by the prominence of cell death, myocardial fibrosis, and inflammation, and is referred to as desmoplakin cardiomyopathy." (PMID 36818425, 2023). "Myocarditis has been previously proposed as a possible clinical presentation of ACM and more specifically DSP-related cardiomyopathies." (PMID 36768812, 2023). "We describe two patients who presented with recurrent episodes of acute chest pain and elevated cardiac markers without coronary artery disease, in whom deep phenotyping and genotyping led to the diagnosis of a desmoplakin (DSP) cardiomyopathy." (PMID 36434384, 2023). "In Maastricht, 17 cases (16%) carried variants that would be considered pathogenic if identified in an individual with cardiomyopathy, all of which were in DCM-associated genes apart from the single case with a DSP-tv." (PMID 36154167, 2022). "Myocardial injury and a distinct pattern of diffuse subepicardial delayed enhancement, even before the onset of left ventricular dilation, appear to be specific clinical findings for DSP-mediated cardiomyopathy [37•, 64, 66]." (PMID 33040239, 2020). "In 8 (66.7%), we found de novo variants in known cardiomyopathy genes (TTN, DSP, SCN5A, TNNC1, TPM1, CRYAB, MYH7)." (PMID 32013205, 2020). "In 8/12 probands (66.7%), we found likely causative variants in known cardiomyopathy genes (TTN, DSP, SCN5A, TNNC1, TPM1, CRYAB, and MYH7), which were confirmed as de novo (six DCM, one HCM, and one RCM case)." (PMID 32013205, 2020). "In 6 of 10 cases of sporadic DCM and in single cases of RCM and HCM, we found de novo mutations in genes previously associated with cardiomyopathy (CRYAB, DSP, MYH7, SCN5A, TNNC1, and TTN)." (PMID 32013205, 2020). "Both of the patients with the DSP variant (HCM562 and HCM591) have another cardiomyopathy gene identified." (PMID 32344918, 2020). "Modeling of cardiomyopathy caused by a desmoplakin (DSP) mutation resulted in fibrosis and cardiac dysfunction and led to identifying the bromodomain and extra-terminal inhibitor INCB054329 as a drug mitigating the desmoplakin-related functional defect." (PMID 40562874, 2025). "Cardiomyopathy genes, including nine prespecified DCM genes including BCL2-associated athanogene-3 (BAG3), desmoplakin (DSP), LMNA, MYH7, sodium voltage-gated channel, alpha subunit 5 (SCN5A), telethonin (TCAP), cardiac troponin C (TNNC1), TNNT2, and TTN, were sequenced." (PMID 40004816, 2025). "It has been reported that DSP cardiomyopathy has a female preponderance, but the influence of this gene is not observed here due to the low inclusion of patients with DSP variants." (PMID 39895490, 2025). "DSP gene-related cardiomyopathy progresses rapidly and has a poor prognosis." (PMID 40709201, 2025). "Initially identified as a diagnostic marker for desmoplakin and filaminC-related cardiomyopathies, the pattern has been reported in nongeneticconditions; nevertheless, it remains an uncommon finding in these diseases." (PMID 40084186, 2025). "Together, these findings highlight the potential of spatial transcriptomics as a powerful tool for linking molecular processes to local remodeling responses and indicate EPAS1 as a critical molecular driver of cardiomyocyte degeneration in the context of DSP-cardiomyopathy." (PMID 40034852, 2025). "Concealed cardiomyopathy in the absence of echocardiographic observation is typical of certain sarcomeric mutations like Filamin C (FLNC) or Desmoplakin (DSP)." (PMID 40429571, 2025).
cardiomyopathy (continued). "Targeted next-generation sequencing of cardiomyopathy-related genes performed when the patient was 22 years old revealed a heterozygous c.4608_4612del5, p.(Arg1537fs) variant in the DSP gene (NM_004415.2), encoding the desmosomal protein desmoplakin." (PMID 39129740, 2024). "However, desmoplakin cardiomyopathy is often misdiagnosed, resulting in significant morbidity and mortality." (PMID 38510230, 2024). "Despite the small size of this cohort, clinical and genetic data suggest that DSP-related cardiomyopathy could be considered a distinct clinical entity characterized by a high arrhythmic burden, variable LVE, and LV scar." (PMID 36768812, 2023). "The phenotype in the Myh6-McmTam:DspF/F mouse model resembles the phenotype of DSP-related cardiomyopathy, which is characterized by the prominence of cell death, inflammation, myocardial fibrosis, left-dominant or biventricular cardiomyopathy, and progressive heart failure." (PMID 36818425, 2023). "As recently described for desmoplakin cardiomyopathy, cardiac inflammation might represent a “hot-phase” in BrS and lead to the natural progression of the disease." (PMID 36292641, 2022). "In a multicenter study that compared the clinical features of patients with DSP and PKP2 genetic variants, the 2010 ITF criteria were insensitive for diagnosing ACM in DSP carriers (34% vs. 49%, p = 0.02), despite the presence of clinically confirmed cardiomyopathy." (PMID 37048743, 2023). "Furthermore, previous case series show that pathogenic DSP variants correlate with ventricular arrhythmias and that left ventricular dysfunction (LVEF < 55%) is strongly associated with sustained ventricular arrhythmias in DSP cardiomyopathies." (PMID 36434384, 2023). "These clinical and genetic data confirm that DSP-related cardiomyopathy may represent a distinct clinical entity characterized by a high arrhythmic burden, variable degrees of LVE, Late Gadolinium Enhancement (LGE) with subepicardial distribution and episodes of myocarditis-like picture." (PMID 36768812, 2023). "Desmoplakin (DSP) is, by far, most associated with inflammation among all the DCM-associated genes, and episodes of myocardial inflammation associated with DSP cardiomyopathy might be confused with (viral) cardiomyopathy." (PMID 37373632, 2023). "Interestingly, desmoplakin cardiomyopathy could also present with BiV involvement phenotype." (PMID 38417843, 2024). "To generate a more severe model of DSP myocarditis and cardiomyopathy with an isogenic control, we used a healthy control hiPSC line to generate biallelic DSP truncations with CRISPR/Cas9, referred to as DSP–/–." (PMID 38768074, 2024). "The modifier roles of the PVs or LPVs in the PKP2, DSP, SCN10A, and others identified in the family members benefit from biological plausibility and the well-established roles of these genes in cardiomyopathies and/or arrhythmias." (PMID 34790974, 2021). "Genes initially attributed to other types of cardiomyopathy, such as MYBPC3 for hypertrophic cardiomyopathy (HCM) and DSP for arrhythmogenic right ventricular cardiomyopathy (ARVC), have been shown to contribute to DCM as well [19, 36, 37•]." (PMID 33040239, 2020). "Lastly, while this paper highlights EPAS1 involvement in DSP-cardiomyopathy progression, it does not address the precise mechanism by which a loss in DSP protein levels induces EPAS1 expression." (PMID 40034852, 2025). "This pattern was commonly linked to desmosomal (DSP) and non-desmosomal (FLNC, LMNA) genes with both NDLVC and DCM and less often associated with ARVC, HCM, or other cardiomyopathies." (PMID 40238040, 2025). "The expression level of DSP is not known to change during aging or the development of other forms of cardiomyopathies or heart failure." (PMID 36818425, 2023). "Furthermore, our study’s limitations prevented us from assessing the full spectrum of symptoms related to DSP- and LMNA-mediated cardiomyopathies." (PMID 35348702, 2022).
cardiomyopathy (continued). "The cardiac phenotype in these mice mimicked desmin-related cardiomyopathies; even though desmin was not directly involved, protein aggregates containing Myozap and other intercalated disc (ID) proteins, such as desmoplakin, were present." (PMID 34899865, 2021). "By performing MCL clustering, we highlighted four subnetworks that could play significant roles in HCM, including one mtDNA-subnetwork and three cardiomyopathy-gene-centered networks: MYBPC3-, MYH7-, and DSP-subnetworks." (PMID 32344918, 2020). "Advances in genetic characterization of cardiomyopathies have identified some desmosomal genes such as DSP and non-desmosomal genes such as Phospholamban, Filamin-C, and Transmembrane Protein 43, that are often associated with biventricular or LV-dominant subforms." (PMID 40021092, 2025). "Whereas the precise molecular mechanism that links DSP variants to ACM has not been fully elucidated, the evidence of inflammatory infiltrates in more than two-thirds of ACM heart samples suggests an important role of recurrent myocarditis as a driver in developing the cardiomyopathy phenotype." (PMID 39336825, 2024). "Interestingly, mice models with specific loss of DSP protein expression in the sinoatrial node pacemaker tissue showed bradycardia, also in the absence of cardiomyopathy, suggesting a possible involvement of DSP in cardiac pacemaker function, with similar roles also in the zebrafish pacemaker." (PMID 38057295, 2023).
myocarditis (38 papers, 2020 to 2026). Myocarditis is a condition that is characterized by inflammation of the heart muscle (myocardium). "Studies have reported that up to 22% of patients initially diagnosed with myocarditis carry such mutations, with DSP, LMNA, and TTN being the most frequently implicated genes." (PMID 41040932, 2025). "Among patients with myocarditis, pathogenic or likely pathogenic variants in the desmoplakin and desmin genes were of particular interest, as they distinguished this group from patients without myocarditis." (PMID 39858598, 2025). "The predominant pathogenic or likely pathogenic variants in patients with myocarditis were observed in the desmoplakin and filamin C genes, in contrast to patients with isolated ARVC." (PMID 39858598, 2025). "In a cohort of 336 patients with acute myocarditis, pathogenic variants for dilated cardiomyopathy or arrhythmogenic cardiomyopathy were found in 8% of patients, with a prevalence of DSP pathogenic variants in patients with normal LVEF." (PMID 39882569, 2024). "It is interesting to mention that, in patients with DSP mutations and recurrent myocarditis, intense physical activity has been described as another potential trigger." (PMID 39336825, 2024). "More specifically, sarcomeric mutations (mainly of the TTN or MYH7 genes) were more frequently associated with complicated myocarditis (21.9%), while desmosomal protein mutations (foremost the DSP gene) were associated with an uncomplicated course (4.2%)." (PMID 39336825, 2024). "A case of probable postvaccination myocarditis has been described in a patient with a left ventricular form of ARVC with a mutation in the DSP gene (predisposing to myocarditis) and a history of two episodes of probable myocarditis." (PMID 39202422, 2024). "Although these studies used DSP disruption as its genetic model of myocarditis, many other genes have been implicated in this process, including TTN, LMNA, FLNC, PKP2, and others." (PMID 38768074, 2024). "Mutations in DSP, a gene encoding the desmosomal protein desmoplakin, have been increasingly implicated in myocarditis." (PMID 38768074, 2024). "In particular, in a cohort of 230 patients (male prevalence: 84%) diagnosed with acute myocarditis, a truncating variant of desmoplakin was present in 3.1% vs. 0.4% of controls (p = 0.001) and was characterized by normal left ventricular ejection fraction." (PMID 39336825, 2024). "In recent years, pathogenic variants in DSP, the gene encoding desmoplakin, have been described in patients presenting with clinical myocarditis." (PMID 38768074, 2024). "The median age for index patients and relatives carrying the DSP variant was higher than that of patients with myocarditis (50 vs. 28 years, P = 0.002 and 38 vs. 28 years, P = 0.03, respectively)." (PMID 37008330, 2023). "In a recent systematic review including 103 ACM patients with these myocarditis-like episodes, DSP was also the most frequently implicated gene (69%)." (PMID 37048743, 2023). "When the genetic background of patients with myocarditis was evaluated, patients with pathogenic DSP variants and family history of ACM were found." (PMID 37008330, 2023). "Recently, a study on 97 patients with acute myocarditis showed that a subgroup of them had pathogenic/likely pathogenic variants on the desmoplakin genes, and these were the patients with a more malignant phenotype." (PMID 36833593, 2023). "Cardiac evaluation of patients with myocarditis, participants carrying the DSP variant, and wild-type family members." (PMID 37008330, 2023). "It is unclear if patients harboring pathogenic DSP variants have episodes of myocardial injury due to desmosomal disruption that triggers inflammatory response mimicking myocarditis." (PMID 37008330, 2023). "Recently, some reports have also suggested the relation between DSP mutations and a family history of recurrent myocarditis." (PMID 34988129, 2021).
myocarditis (continued). "Interestingly, the presence of DSP variants in patients with acute myocarditis was reported to be associated with worse outcomes in acute myocarditis patients, as DSP mutation carriers had a higher risk of ventricular arrhythmias and recurrent myocarditis." (PMID 39786662, 2025). "In patients, the DSP mutations are present throughout their lifetimes, suggesting additional stressors contribute to manifesting myocarditis episodes, which histopathologically are characterized by myocardial necrosis and immune cell, typically lymphocytic, infiltrate." (PMID 38768074, 2024). "In DSP gene mutation carriers, cardiac inflammation is detected using cardiac imaging, specifically 18F-fluorodeoxyglucose positron emission tomography, and this inflammatory signature has been referred to as a “sterile” myocarditis-like process." (PMID 38768074, 2024). "Additionally, pathogenic variants of desmoplakin should bevigilant in cases of recurrent myocarditis or a family history of myocarditis." (PMID 39742233, 2024). "CRP and TnI levels were higher in patients with myocarditis than in index patients (19 vs. 3 mg/L, P = 0.07 and 6,443 vs. 15 ng/L, P < 0.001, respectively) and family members with the DSP variant (19 vs. 3 mg/L, P < 0.001 and 6,443 vs. 3 ng/L, P < 0.001, respectively)." (PMID 37008330, 2023). "Previous studies have suggested that pathogenic DSP variants might play a unique role in myocarditis in ACM." (PMID 37288269, 2023). "DSP pathogenic variants are also associated with an acute myocarditis-like presentation in ACM." (PMID 38137480, 2023). "Interestingly, in patients with DSP mutation and recurrent myocarditis, intense physical activity has been described as another potential trigger, thus reinforcing the need to consider genomic-environment interaction." (PMID 33961130, 2021). "Also, AC due to desmoplakin (DSP) mutation was found to be associated with intermittent myocardial inflammatory episodes clinically similar to those of myocarditis." (PMID 33961130, 2021). "Moreover, DSP mutation also seems to identify patients at high risk of recurrent myocarditis." (PMID 39336825, 2024). "We present two cases of young male patients, both with mutations in the DSP and LMNA genes, who initially presented with symptoms of myocardial inflammation." (PMID 41040932, 2025). "As a whole, gene expression changes in DSP–/– EHTs were consistent with a pathological role for activation of innate immunity and inflammation as a disease mechanism, mirroring myocarditis-like findings." (PMID 38768074, 2024). "In this view, it is interesting to highlight the role of e.g. DSP, DSG2 and PKP2 mutations in acute (recurrent) myocarditis." (PMID 39347728, 2024). "This review aims to synthesize current knowledge on the genetic underpinnings of myocarditis, with an emphasis on desmoplakin-related arrhythmogenic cardiomyopathy, to enhance clinical understanding and inform future research directions." (PMID 39336825, 2024). "DSP p.E1597X was identified in a woman in her early 20s who was diagnosed with myocarditis after presenting with bradycardia and heart failure." (PMID 38768074, 2024). "The references of all identified articles were reviewed to look for additional papers of interest, to extrapolate the more recent available data on desmoplakin-related myocarditis, with a slight view of other possible genes involved." (PMID 39336825, 2024). "Original reports, meta-analyses, and review articles in peer-reviewed journals up to July 2024 regarding myocarditis, desmoplakin, autoimmunity, and genetic background were incorporated into the search strategy." (PMID 39336825, 2024). "As for ACM, pathogenic variants in desmosomal genes, namely plakoglobin (JUP), desmoplakin (DSP), plakophilin (PKP2), desmoglein (DSG2), and desmocollin (DSC), are depicted as the main cause, in turn displaying extensive overlap with myocarditis." (PMID 37189393, 2023).